CFTR (CF transmembrane conductance regulator)
Diseases named in the same sentence as CFTR in open-access papers (continued):
Sharing a sentence is not in itself a finding about the gene and the disease.
cystic fibrosis (continued). "Cystic fibrosis is an autosomal recessive genetic disorder caused by CFTR’s (Cystic Fibrosis Transmembrane Regulator) gene mutation." (PMID 37420288, 2023). "CFTR functions as an anion channel and is critical for fluid and electrolyte homeostasis, and its mutations result in cystic fibrosis that affects the respiratory, digestive, endocrine, and reproductive system." (PMID 37574502, 2023). "Cystic fibrosis is a monogenic disease caused by the mutation of cystic fibrosis transmembrane conductance regulator (CFTR) gene, an anion channel-protein coding sequence that plays a crucial role in the airway surface liquid homeostasis." (PMID 37077918, 2023). "Cystic fibrosis is a multi-organ disease caused by loss-of-function mutations in CFTR (which encodes the CF transmembrane conductance regulator ion channel)." (PMID 38075070, 2023). "Lumacaftor (Vx-809) is the first drug approved for the treatment of cystic fibrosis in patients homozygous for the most common cystic fibrosis transmembrane Conductance Regulator (CFTR), mutated F508del-CFTR." (PMID 36835664, 2023). "Cystic fibrosis is caused by mutations in the cystic fibrosis transmembrane conductance regulator (CFTR) gene and affects mostly the lung, but also other organs." (PMID 36625583, 2023). "Elexacaftor is recommended for the treatment of cystic fibrosis in individuals 12 years of age and older who have at least one F508del mutation in the CFTR gene." (PMID 37631077, 2023). "In 2018, the Cystic Fibrosis Foundation Patient Registry reported that 3.1% of pwCF carry more than two CFTR variants." (PMID 37445855, 2023). "CFTR, which is a cAMP-dependent Cl− channel, is expressed in various epithelial cells, and CFTR mutations cause cystic fibrosis." (PMID 38203460, 2023). "Cystic Fibrosis is an autosomal recessive genetic disease caused by mutations in the CFTR gene, coding for the CFTR chloride channel." (PMID 37298560, 2023). "Cystic fibrosis is a recessive genetic disorder caused by pathogenic variants of the cystic fibrosis transmembrane conductance regulator (CFTR) gene." (PMID 37165031, 2023). "In the Russian Federation, in 2022, a mass screening of the CFTR gene was conducted among 810 patients aged 2 to 39 years with a diagnosis of “cystic fibrosis caused by a mutation of p.Phe508del in a homozygous state” by MLPA." (PMID 38203285, 2023). "In cystic fibrosis, inherited mutations in the cystic fibrosis transmembrane regulator (CFTR) chloride channel cause accumulation of thick mucus in the airways and gastrointestinal tract." (PMID 37284754, 2023). "Deficient cystic fibrosis transmembrane conductance regulator (CFTR) activity in people with cystic fibrosis results in chronic airway infection and neutrophilic inflammation, leading to airway wall injury and bronchiectasis." (PMID 37568199, 2023). "One of the most common genetic disorders affecting host defense in the airway is cystic fibrosis resulting from mutations in the CF transmembrane conductance regulator (CFTR) chloride and bicarbonate ion channel." (PMID 37318849, 2023). "FIP is a late-stage pancreatic disease observed in individuals with cystic fibrosis, and it is primarily caused by a deficiency or malfunction of the cystic fibrosis transmembrane conductance regulator (CFTR) protein in the pancreatic duct epithelium (PDE)." (PMID 37809324, 2023). "The authors of this article analyzed the available literature with the results of studying the prevalence of complex alleles of the CFTR gene among patients with cystic fibrosis, and their pathogenicity and influence on targeted therapy with CFTR modulators." (PMID 38203285, 2023). "Cystic fibrosis is a complex, heterogeneous, multi-organ disorder caused by defects in the CF transmembrane conductance regulator (CFTR) gene." (PMID 36830128, 2023). "According to the Registry of Russian Patients with Cystic Fibrosis, the L138ins variant is one of the common genetic variants of the CFTR gene in Russian patients with CF." (PMID 37510311, 2023).
cystic fibrosis (continued). "Cystic fibrosis transmembrane conductance regulator (CFTR) was originally identified as a product of a gene mutated in patients with cystic fibrosis." (PMID 36696993, 2023). "Patients with cystic fibrosis and at least one F508del-CFTR mutation are treated with this drug in conjunction with tezacaftor and ivacaftor." (PMID 37631077, 2023). "Cystic fibrosis is an autosomal recessive disease, caused by sequence variations in the gene encoding for the CF transmembrane regulator (CFTR), a channel protein that regulates chloride and bicarbonate transport." (PMID 36831163, 2023). "According to our data, GSEA also showed that fibroblasts in the defunctioned intestine were enriched of inflammatory and fibrosis‐related signalling pathways (e.g. defective CFTR causes cystic fibrosis and TNF‐mediated signalling pathway)." (PMID 37400975, 2023). "Cystic fibrosis is a life-limiting genetic disorder caused by a mutation in the cystic fibrosis transmembrane conductance regulator gene (CFTR)." (PMID 36752587, 2023). "Cystic fibrosis is a life-limiting hereditary disease caused by loss-of-function mutations in the cystic fibrosis transmembrane conductance regulator (CFTR) gene." (PMID 37014818, 2023). "Cystic fibrosis is a rare genetic disease caused by mutations on CFTR gene which encodes for a protein that functions as chloride ion channel, necessary to maintain correct trans- epithelial fluid transport." (PMID 36923406, 2023). "Cystic fibrosis is the most common rare multiorgan disease caused by a mutation in the CFTR (cystic fibrosis transmembrane conductance regulator) gene, which regulates the CFTR protein, a cyclic adenosine monophosphate-regulated Cl− channel." (PMID 36941680, 2023). "Cystic fibrosis is a genetic disease caused by mutations in the cystic fibrosis transmembrane conductance regulator (CFTR) gene, which encodes a channel responsible for the transport of chloride and bicarbonate ions across the epithelial apical cell surface." (PMID 37874846, 2023). "Today, nearly 90% of people with cystic fibrosis (pwCF) have mutations eligible for either CFTR modulator monotherapy or combination therapy." (PMID 37408761, 2023). "Another example of a genetic metabolic disease is cystic fibrosis, which is caused by mutations in the cystic fibrosis transmembrane conductance regulator (CFTR) gene." (PMID 37445852, 2023). "Cystic fibrosis is a rare genetic disease caused by genetic variants of the cystic fibrosis transmembrane conductance regulator (CFTR) [...]." (PMID 37175472, 2023). "Cystic fibrosis is a predominant genetic disease in Caucasian populations, caused by mutations in the gene encoding the CF transmembrane conductance regulator (CFTR) protein." (PMID 36971560, 2023). "Specifically, the CFTR (cystic fibrosis transmembrane conductance regulator) protein is a chloride channel in the plasma membrane of epithelial cells, and certain CFTR mutations are the monogenic cause of cystic fibrosis." (PMID 36835433, 2023). "Recently, small molecule CFTR modulators were discovered that improve the function of some mutant forms of CFTR protein associated with cystic fibrosis." (PMID 36625656, 2023). "Cystic fibrosis is an autosomal recessive respiratory genetic disease caused by mutation in the cystic fibrosis transmembrane conductance regulator (CFTR) gene." (PMID 36891265, 2023). "Cystic fibrosis is a life-limiting monogenic disease caused by loss-of-function mutations in the CF transmembrane conductance regulator gene, CFTR." (PMID 37235648, 2023). "Rectal suction biopsies were obtained from patients with cystic fibrosis who participated in the Trikafta trial and had a virtual loss of CFTR function, as evidenced by electrophysiological studies of their rectal biopsies." (PMID 37762516, 2023). "Among the most prominent examples is the development of small molecule therapies using a simple cell-based in vitro assay for CFTR deficiency to develop therapeutics for cystic fibrosis." (PMID 37747131, 2023).
cystic fibrosis (continued). "Any mutation in the gene that encodes cystic fibrosis transmembrane conductance regulator (CFTR) causes lung disease, i.e., cystic fibrosis." (PMID 37514158, 2023). "Sodium phenylbutyrate is known to stabilize the mutant cystic fibrosis transmembrane conductance regulator (CFTR) protein in the ER and circumvent the phenotype associated with destabilizing mutations in cystic fibrosis." (PMID 35362847, 2023). "The mutation of the Transmembrane Conductance Regulator (CFTR) gene is the underlying cause of cystic fibrosis, which causes dysfunctional chloride ion transport." (PMID 37686009, 2023). "MAST2 was shown to form a complex with the key factor associated with cystic fibrosis, the cystic fibrosis transmembrane conductance regulator (CFTR)." (PMID 37569286, 2023). "Cystic fibrosis is a heritable disease caused by mutations in the cystic fibrosis transmembrane conductance regulator (CFTR)." (PMID 37404016, 2023). "Cystic fibrosis, which is the predominant genetic disease in European populations, is caused by mutations in the gene encoding the cystic fibrosis transmembrane conductance regulator (CFTR) protein." (PMID 37228437, 2023). "Gene editing offers the opportunity to repair or modify mutations associated with inherited diseases such as cystic fibrosis, a disorder caused by mutations in CF transmembrane conductance regulator (CFTR)." (PMID 38052872, 2023). "Cystic fibrosis is a multisystem autosomal recessive disease that is caused by mutations in the cystic fibrosis transmembrane conductance regulator (CFTR) gene, resulting in a dysfunctional CFTR protein." (PMID 37242730, 2023). "Cystic fibrosis is a genetic disorder mainly caused by mutation in the gene for the cystic fibrosis transmembrane conductance regulator (CFTR) affecting 100,000 worldwide." (PMID 37956290, 2023). "Cystic Fibrosis is one of the most common genetic disorders caused by mutations in the cystic fibrosis conductance regulator (CFTR) gene, which encodes for an apical epithelial chloride channel." (PMID 37763754, 2023). "The pathogenesis of cystic fibrosis is now clearly proposed as the mutation of the Cystic Fibrosis Transmembrane Conductance Regulator (CFTR) gene, which was first described in 1989." (PMID 38186649, 2023). "Cystic fibrosis, a hereditary condition inherited in an autosomal recessive manner, originates from genetic mutations within the CFTR gene." (PMID 37893045, 2023). "F508del (c.1521_1523delCTT; p.Phe508del) variant is the most common CFTR gene mutation both in Russian men with cystic fibrosis and patients with CBAVD syndrome (44.4% and 52.0% of all detected mutations in these groups, respectively)." (PMID 38003474, 2023). "Various mutations affecting the CFTR gene are responsible for cystic fibrosis and approximately 10% of CF patients worldwide have stop mutations in the protein-coding gene sequence." (PMID 37446121, 2023). "Cystic fibrosis is a life-threatening inherited disease related to a mutation in the CFTR gene, that leads to serious health complications such as chronic pulmonary infections, pancreatic insufficiency, dysfunction of the sweat glands and reproductive system." (PMID 37711888, 2023). "If a patient presents with symptoms suggestive of cystic fibrosis and obstructive azoospermia with a CFTR gene mutation or any other genetic abnormality, it is essential to counsel the couple about the potential risk of disease transmission." (PMID 37736241, 2023). "Cystic fibrosis transmembrane conductance regulator (CFTR) modulators, a new series of therapeutics that correct and potentiate some classes of mutations of the CFTR, have provided a great therapeutic advantage to people with cystic fibrosis (pwCF)." (PMID 36902441, 2023). "In patients with Cystic Fibrosis, a recessive genetic disorder caused by mutations in the cystic fibrosis transmembrane conductance regulator (CFTR), accumulation of the misfolded CFTR induces a perpetual ER stress." (PMID 37711626, 2023).
cystic fibrosis (continued). "The multi-organ disease cystic fibrosis is caused by mutations in the gene encoding the CF transmembrane conductance regulator (CFTR) protein, a cAMP-regulated chloride and bicarbonate channel." (PMID 38139828, 2023). "Cystic fibrosis transmembrane conductance regulator (CFTR) is responsible for cystic fibrosis when it is mutated." (PMID 38139010, 2023). "Cystic fibrosis is an autosomal recessive disorder caused by mutations in the CF transmembrane conductance regulator (CFTR) gene and is the most common lethal Mendelian disease in populations with European ancestry." (PMID 37052589, 2023). "These enclose several classes of small molecules that bind to CFTR, enhancing or even restoring the function of specific cystic fibrosis-causing mutants." (PMID 36979360, 2023). "Cystic fibrosis, which is also characterized by bronchiectasis, is caused by loss of function mutations in the cystic fibrosis transmembrane conductance regulator (CFTR) protein." (PMID 36615184, 2023). "The monogenic, recessive disease cystic fibrosis is caused by mutations of the CF transmembrane conductance regulator (CFTR) gene that inhibits expression, activity, or trafficking of the CFTR anion channel at the apical surface of epithelial cells." (PMID 37373505, 2023). "In these cases, panels should include at least the prevalence of approximately 85% of the CFTR mutations detected in the specific population, according to the Italian Society for the Study of Cystic Fibrosis." (PMID 37628659, 2023). "The Cystic Fibrosis Mutation Database has published more than 2000 CFTR gene mutations, of which 380 are verified as pathogenic." (PMID 37274793, 2023). "Cystic fibrosis is one of the most frequent geneticdiseases,caused by dysfunction of the CF transmembrane conductance regulator(CFTR) chloride channel." (PMID 37019688, 2023). "Cystic fibrosis is a multisystem progressive autosomal recessive disease caused by a mutation in the cystic fibrosis transmembrane conductance regulator (CFTR) gene causing impairment of chloride transport." (PMID 37875496, 2023). "Cystic fibrosis is caused by variants in the CFTR gene resulting in impaired anion transport across epithelial barriers and consequently to multi-organ disease including the lungs, liver, and gastrointestinal tract." (PMID 37024122, 2023). "They made one intestinal organoid for the F508del mutation and another with the R785* mutation of the CFTR gene, mutations causing cystic fibrosis." (PMID 36831203, 2023). "Cystic fibrosis is the most common, life-limiting autosomal recessive disease in Caucasians and is caused by defects in the production of the CFTR ion channel." (PMID 36674441, 2023). "CFTR, the anion channel mutated in cystic fibrosis patients, is a model ABC protein whose ATP-driven conformational cycle is observable at single-molecule level in patch-clamp recordings." (PMID 37782012, 2023). "Cystic fibrosis caused by CFTR mutation is closely related to the development of COPD, and abnormal S1P signaling was reported in a CFTRF508del mutant mouse model of cystic fibrosis." (PMID 36226596, 2023). "Only one of them was “pathogenic” and a singleton variant (i.e., heterozygous in a person) of the CFTR gene which are known to cause the disease cystic fibrosis, a condition that affects the respiratory and digestive systems." (PMID 38060463, 2023). "A highly successful example is the development of small molecule therapies using a simple cell-based in vitro assay for CFTR deficiency to develop therapeutics for cystic fibrosis." (PMID 37747131, 2023). "Cystic fibrosis is among the most common, life-limiting inherited disorders, caused by mutations in the CF transmembrane conductance regulator (CFTR) gene." (PMID 37052589, 2023). "Loss-of-function mutations in CFTR cause cystic fibrosis, a multi-organ disease of chronic inflammation, mucus obstruction and bacterial infection that leads to a gradual decline in lung function." (PMID 35060604, 2022).